CPEB4 (cytoplasmic polyadenylation element binding protein 4)
Diseases named in the same sentence as CPEB4 in open-access papers (continued):
Sharing a sentence is not in itself a finding about the gene and the disease.
melanoma (continued). "Given the higher sensitivity of melanoma cells to CPEB4 depletion, we decided to address the possibility of lineage-specificity in the requirement of this protein." (PMID 27857118, 2016). "RNA immunoprecipitation, sequencing of bound transcripts and poly(A) length tests link the melanoma-specific functions of CPEB4 to signalling hubs specifically enriched in this disease." (PMID 27857118, 2016). "Together, these results demonstrate a new role of CPEB4 in G1/S transition in melanoma superseding a secondary function in mitotic control." (PMID 27857118, 2016). "Downregulation of BUB1B, CDK1 and DEK provides a mechanistic explanation for the aberrant spindles and defects in cytokinesis observed after sustained depletion of CPEB4 in melanoma cells." (PMID 27857118, 2016). "This study elucidated that L-Shikonin may regulate melanoma-specific markers, melanosomes, tyrosine kinases related to abnormal tyrosine metabolism, and melanoma through multiple targets such as CPEB4 and HNRNPUL1." (PMID 39771522, 2024). "CPEB4 plays a role in modulating the proliferation and metastasis of melanoma cells, and HNRNPUL1 is implicated in regulating tyrosine kinases linked to aberrant tyrosine metabolism in melanoma." (PMID 39771522, 2024). "CPEB4 is overexpressed in pancreatic ductal adenocarcinoma and melanoma." (PMID 32967226, 2020). "Therefore, we selected to perform RNA immunoprecipitations (RIP) using protocols we have proven efficient for RBPs such as the cytoplasmic polyadenylation factor CPEB4 in melanoma cells." (PMID 29269732, 2017). "Focusing on solid tumours, melanoma cells were found among the highest expressors of CPEB4." (PMID 27857118, 2016). "Single-cell quantifications in cultured cells and subcutaneous melanoma lesions in mice demonstrated that although consistent, mitotic defects in CPEB4-downregulated melanoma cells were infrequent, with <10% increase over basal levels detected in the shControl (shC) cells." (PMID 27857118, 2016). "Next, we interrogated whether the depletion of CPEB4 in melanoma cells could be counteracted by a compensatory upregulation of other CPEBs." (PMID 27857118, 2016). "Yet, one of the most unexpected findings of this work was the acute abrogation of cell proliferation in CPEB4-downregulated melanoma cells (a feature we could trace back to normal melanocytes)." (PMID 27857118, 2016). "However, melanoma cells appear to acquire additional dependencies on CPEB4 during tumour progression." (PMID 27857118, 2016). "Overall, these results suggest that melanoma cells may hijack roles of CPEB4 in cell proliferation already present in normal melanocytes." (PMID 27857118, 2016). "Therefore, the histological and functional results of this study bring physiological relevance to our initial computational data which had revealed a particular enrichment of CPEB4 in melanoma, also characteristic for RAB27A." (PMID 27857118, 2016). "In both cases (particularly for MITF-deficient melanoma cells) RAB27A levels were reduced in the absence of CPEB4." (PMID 27857118, 2016). "However, CPEB4 was found upregulated already at early stages in melanoma development." (PMID 27857118, 2016). "Simultaneously, three of these proteins intersected with established melanoma-related targets, namely RPN1, CPEB4, and HNRNPUL1." (PMID 39771522, 2024). "We have recently identified two 3′ end-interacting factors (the cytoplasmic polyadenylation protein CPEB4, and the translation modulator UNR) with key roles in melanoma progression." (PMID 29269732, 2017). "As the case of melanomas, melanocytes also expressed CPEB1, CPEB2 and CPEB3, but these proteins appear to be unable to compensate for CPEB4 depletion." (PMID 27857118, 2016). "In addition to CSDE1, several RBPs have been shown to play roles in melanoma progression, including CELF, CPEB4, IGF2BP1, IGF2BP3, NOVA1 and DDX3X, among others." (PMID 38396995, 2024).
melanoma (continued). "Therefore, we set to test the functional impact of CPEB4 in the levels and polyadenylation status of both, MITF and RAB72A in additional melanoma cell lines and in tissue specimens (respectively)." (PMID 27857118, 2016). "Furthermore, additional RNA-immunoprecipitations demonstrated binding of CPEB4 to the 3′-UTR of BUB1B, CDK1 and DEK mRNAs in melanoma cells." (PMID 27857118, 2016). "Interestingly, depletion assays demonstrated that the requirement of CPEB4 to maintain MITF levels was also found to extend to normal melanocytes, the cells or origin of melanomas." (PMID 27857118, 2016). "Therefore, the depletion of CPEB4 was assessed in melanoma cells cultured as monolayers in the absence of other cell types." (PMID 27857118, 2016). "In addition, poly(A) tail tests (RNA-ligation-coupled RT-PCR) confirmed the shortening of the poly(A) tail and the destabilization of these three mRNAs upon CPEB4 depletion in melanoma, but not in other cell types." (PMID 27857118, 2016). "Next, biopsies from lesions containing non-malignant melanocytes (nevi) and from melanomas at different stages of progression (N=56), were analysed to define whether CPEB4 upregulation is an early or late event in this disease." (PMID 27857118, 2016). "Thus, while known targets of CPEB4 such as the metallothionein proteins MT2A and MT1E were found in both cell types, 93% of the CPEB4-bound transcripts in melanoma (that is, 312/331) had not been reported in RWP1." (PMID 27857118, 2016). "However, these genes cannot account for the acute and melanoma-enriched G1 arrest after CPEB4 downregulation, and could not explain why melanomas would be more dependent on this polyadenylation factor than other tumour types." (PMID 27857118, 2016). "Consequently, it could perhaps have been anticipated that melanomas behaved in a similar manner as aggressive pancreatic cancers, namely, being able to sustain CPEB4 depletion without affecting cell cycle progression." (PMID 27857118, 2016). "Similarly, there are no reports of the CPEB family members CPEB2, CPEB3 and CPEB4 in melanoma." (PMID 27857118, 2016). "Intriguingly, while CPEB4 was not exclusive of melanoma, pairwise analyses identified statistically significant differences with 18 tumour types, including glioblastoma and pancreatic cancer, where CPEB4 functions and targets have been addressed in more detail." (PMID 27857118, 2016). "Indeed, our data revealed that melanomas -as other tumour types- express other CPEB family members (particularly CPEB1 and CPEB2), which could have acted in a compensatory manner in the absence of CPEB4." (PMID 27857118, 2016).
pancreatic ductal adenocarcinoma (8 papers, 2015 to 2025). An infiltrating adenocarcinoma that arises from the epithelial cells of the pancreas. "In another study, CPEB4 gene expression was reported to increase in pancreatic ductal carcinoma but decreased in hepatocellular carcinoma." (PMID 33237662, 2021). "What’s more, elevated CPEB4 expression correlates with increased malignancy, tumor growth, and vascularization in pancreatic ductal adenocarcinoma and glioblastoma." (PMID 33146632, 2020). "Nevertheless, CPEB4 seems to play paradoxical roles in cancers–an oncogenic promoter in pancreatic ductal adenocarcinoma (PDA) and glioblastomas but a tumor suppressor in hepatocellular carcinoma (HCC)." (PMID 27158894, 2016). "CPEB4 is upregulated in pancreatic ductal adenocarcinoma (PDA) and glioblastoma but downregulated in HCC." (PMID 27158894, 2016). "Ortiz-Zapater et al6 found that CPEB4 was overexpressed in pancreatic ductal adenocarcinomas, supporting tumor growth, vascularization, and invasion." (PMID 26166131, 2015). "Moreover, in a genome-wide screening study, CSAG2 was found to be coimmunoprecipitated with CPEB4 in pancreatic ductal adenocarcinoma cells line, although remains to be validated further." (PMID 33519462, 2020). "Moreover, CPEB4, one member of CPEBs, has been shown to play a key role in the progression of pancreatic ductal adenocarcinoma, glioblastoma, glioma and gastric cancer." (PMID 33519462, 2020). "In pancreatic ductal adenocarcinoma (PDA), overexpression of CPEB4 promotes poly(A) elongation and translational activation for the mRNA encoding tPA, which is a key regulator of PDA malignancy." (PMID 32967226, 2020). "CPEB4 exhibits dual roles in various tumors, functioning as an oncogene in certain cases like hepatocellular carcinoma (HCC) and as a pro-carcinogen in others such as pancreatic ductal adenocarcinoma and glioblastoma." (PMID 40084246, 2025). "Additionally, these investigators used CPEB4 shRNA to silence its expression and demonstrated that CPEB4 promotes tumor growth and vascularization in the T98 cell line and in the RWP-1 pancreatic ductal adenocarcinoma cell line." (PMID 26166131, 2015).
autism (7 papers, 2019 to 2026). Persistent deficits in social interaction and communication and interaction as well as a markedly restricted repertoire of activity and interest as well as repetitive patterns of behavior. "Moreover, a recent study has shown that CPEB4 protein is an important regulator of a large number of autism-associated genes." (PMID 31691811, 2020). "Various genes enriched in modern humans are disease-relevant genes like CHD8 and CPEB4 in autism spectrum, HTT in Huntington’s disease, FOXP2 in language impairment." (PMID 36550402, 2022). "For example, an exon encoding a regulatory phosphorylation site in the RNA-binding protein CPEB4 is skipped <30% of the time but this skipping is correlated with if not causative for autism." (PMID 38048343, 2023). "Interestingly, the misregulation of alternative splicing by a microexon in CPEB4, a key protein that coordinates the expression of hundreds of genes required for neuronal activity, has been identified in the brains of individuals with autism." (PMID 38791210, 2024).
breast cancer (7 papers, 2016 to 2023). A primary or metastatic malignant neoplasm involving the breast. "Overexpression of CPEB4 is associated with tumor growth, vascularization, migration, invasion and metastasis in breast cancer patients, causing an upregulation of Vimentin expression and promoting EMT, invasion and migration of breast cancer cells." (PMID 36052258, 2022). "In eQTL analysis of METABRIC breast cancer tissue data, CPEB4 was found to be associated with SNP rs17695092, and the same SNP had CPEB4 also as an INQUISIT target gene." (PMID 32714364, 2020). "In addition, putative breast cancer risk associated SNPs (p < 1 × 10–5) in the region of two T-UCRs, uc.184 and uc.313, located in protein coding genes CPEB4 and TIAL1, respectively, targeted these genes in INQUISIT and in eQTL analysis." (PMID 32714364, 2020). "Our results imply that CPEB4 may also play a role in the breast cancer development as the intronic SNP rs17695092 associates with both reduced CPEB4 expression, and reduced breast cancer risk." (PMID 32714364, 2020). "CPEB4 is overexpressed in breast cancer cells and alters the proliferative state of the tumor by affecting the expression level of its target mRNA." (PMID 36052258, 2022). "For example, CPEB4 can promote breast cancer metastasis through upregulation of Vimentin and facilitate the migration and invasion of lung cancer cells through activation of the AKT pathway." (PMID 35317822, 2022). "We report here putative breast cancer risk SNPs predicted to functionally target GABPB1-AS1 lncRNA, and associating with its expression, as well as SNPs in two genes, CPEB4 and TIAL1, hosting ultraconserved regions, uc.184 and uc.313, respectively." (PMID 32714364, 2020). "For example, CPEB4 can regulate tumour cell invasion and migration by regulating Vimentin expression in breast cancer; ZEB1-mediated EMT may be involved in CPEB4-promoted cell proliferation, invasion, and metastasis in gastric cancer." (PMID 35317822, 2022). "There are no previous reports of CPEB4 affecting breast cancer risk, but overexpression of CPEB4 is reported in breast cancer, and the overall survival of patients with high expression of CPEB4 is shorter." (PMID 32714364, 2020). "Cytoplasmic polyadenylation element binding protein 4 (CPEB4), which is a member of the CPEB family, has been shown to be aggrandized in many malignant tumors, such as gastric cancer and breast cancer." (PMID 33106913, 2021). "Ectopic CPEB4 expression has been suggested to promote EMT, migration and invasion of breast cancer cells, while silencing the expression of CPEB4 reduces these events." (PMID 32714364, 2020). "However, the specific role and mechanisms of CPEB4 in breast cancer have not been fully investigated and reported in this regard." (PMID 36052258, 2022).
glioblastoma (6 papers, 2015 to 2025). The most malignant astrocytic tumor (WHO grade IV). "Additionally, CPEB4 mRNA is upregulated in pancreatic carcinomas and glioblastomas, while CPEB3 mRNA is consistently downregulated in digestive tract tumors." (PMID 33146632, 2020). "Notably, positive CPEB4 expression was observed in 64/64 (100%) glioblastoma (WHO IV) samples." (PMID 26166131, 2015).
hepatocellular carcinoma (6 papers, 2016 to 2025). A malignant tumor that arises from hepatocytes. "Studies have shown that knocking down CPEB4 in HepG2 hepatocellular carcinoma cells promotes colony formation in vitro." (PMID 40084246, 2025). "When liver samples taken from 125 hepatocellular carcinoma patients were compared with 49 controls, it was reported that the protein level of CPEB4 increased in early stage hepatocellular carcinoma and decreased in late stage hepatocellular carcinoma." (PMID 33237662, 2021). "However, a tumor-suppressor role of CPEB4 was demonstrated in hepatocellular carcinoma and non-small cell lung cancer." (PMID 34976999, 2021). "However, CPEB4 is downregulated in hepatocellular carcinoma and non-small cell lung cancer." (PMID 34976999, 2021).
Obesity (6 papers, 2021 to 2026). Accumulation of substantial excess body fat. "In summary, the collective data paint a compelling picture: genetic variations in CPEB4 predispose individuals to obesity-related traits, while the protein itself is overexpressed in adipose tissue in obese states." (PMID 41596407, 2026). "It functions as a critical pro-adipogenic factor at the cellular level, and its inhibition, as shown in knockout models, can protect against diet-induced obesity, inflammation, and associated metabolic dysregulation, positioning CPEB4 as a potential therapeutic target for metabolic diseases." (PMID 41596407, 2026). "This pattern is recapitulated in animal models of obesity, where CPEB4 expression is consistently upregulated in various adipose tissue depots." (PMID 41596407, 2026). "Of note, our studies highlight the role of CPEB4 in the stress resolution of obesity-driven fibrosis and CLD." (PMID 34944111, 2021). "Indeed, CPEB4 drives a posttranscriptional reprogramming in adipocytes of white adipose tissue under obesity conditions." (PMID 34912244, 2021). "Interestingly, recent studies from our group using a murine model of diet-induced obesity placed CPEB4 as an important regulator of adipose tissue expansion." (PMID 34944111, 2021). "In addition, hypermethylation of 18 obesity candidate genes was observed, of which two of the Cytoplasmic Polyadenylation Element Binding Protein 4 (CPEB4) and Serologically Defined Colon Cancer Antigen 8 (SDCCAG8) had reduced expression." (PMID 34884790, 2021). "Genome-wide association studies have identified specific single-nucleotide polymorphisms (SNPs) near the CPEB4 gene that show a strong statistical association with key metabolic traits, particularly elevated waist-to-hip ratio (WHR) and body mass index (BMI)—two major indicators of obesity." (PMID 41596407, 2026).
pancreatic cancer (6 papers, 2016 to 2024). "CPEB4 was first identified as a pro-oncogenic factor and promoted translation of tissue plasminogen activator (tPA) RNA to support metastatic invasion of pancreatic cancer cells." (PMID 27158894, 2016). "CPEB4 was first identified to be upregulated and acted as an oncogene in pancreatic cancer." (PMID 34976999, 2021). "In contrast to CPEB4, whose oncoprotein function in pancreatic cancer has been identified 36, the biological function and clinical significance of CPEB1 in pancreatic cancer are yet to be elucidated." (PMID 38904009, 2024). "This was unexpected considering the reported situation in pancreatic cancer cells, where CPEB4 depletion delayed, but did not abrogate xenograft formation." (PMID 27857118, 2016). "CPEB4-KD decreased proliferation and colony formation of RWP-1 pancreatic cancer cells in vitro and tumorigenesis in vivo but increased in vitro migration and invasion of SMMC-7721 liver cancer cells, which suggests that CPEB4 could promote or suppress tumorogenesis depending on the cancer type." (PMID 27158894, 2016).